LINC01488 (long independently transcribed non-coding RNA 1488)
Synonyms: CUPID1; BRCAT8
Gene: Long non-coding RNA gene on chromosome 11 (69,481,662 to 69,494,952, forward strand). Ensembl gene ENSG00000285094.
Diseases named in the same sentence as LINC01488 in open-access papers:
LINC01488 is named in the same sentence as 5 diseases in open-access papers, as found by Europe PMC text mining. Sharing a sentence is not in itself a finding about the gene and the disease. The quoted sentences say what the papers report.
breast carcinoma (1 paper, 2022). "LINC01488 has been shown to mediate breast cancer risk by playing a role in homologous recombination (HR)-mediated DNA repair." (PMID 35982125, 2022).
hepatoma (1 paper, 2020). "However, our data showed that that LINC01488 positively regulates miR-124-3p and miR-138-5p to reduce vimentin expression in hepatoma cells, indicating that lincRNAs not only act as miRNA sponges but also regulators to modify target mRNA levels." (PMID 32575745, 2020).
liposarcoma (1 paper, 2020). A usually painless malignant tumor that arises from adipose tissue. "Furthermore, LINC01488 is reported to bind translocated in liposarcoma (TLS) and induce transcriptional repression through HAT inhibitory activity in addition to negatively regulating Cyclin D1 transcription to inhibit cell growth." (PMID 32575745, 2020).
liver cancer (1 paper, 2020). An epithelial or non-epithelial malignant neoplasm that arises from the liver. "Next, we investigated the mechanisms by which LINC01488 negatively regulates metastasis in liver cancer cells." (PMID 32575745, 2020). "Based on the results, we suggest that LINC01488 negatively regulates the epithelial–mesenchymal transition (EMT) in liver cancer cells." (PMID 32575745, 2020).
tumor (1 paper, 2020). "Our results collectively indicate that LINC01488 acts as a tumor suppressor that inhibits metastasis and tumorigenesis in HCC via the miR-124-3p/miR-138-5p/vimentin axis." (PMID 32575745, 2020). "Our experimental results clearly suggest that upregulation of LINC01488 leads to suppressed tumor cell mobility." (PMID 32575745, 2020). "Our collective results support a tumor suppressor role of LINC01488 in HCC." (PMID 32575745, 2020). "In conclusion, these results pointed out LINC01488 acts as a tumor suppressor in HCC." (PMID 32575745, 2020).